GABRA1 (gamma-aminobutyric acid type A receptor subunit alpha1)
Diseases named in the same sentence as GABRA1 in open-access papers (continued):
Sharing a sentence is not in itself a finding about the gene and the disease.
epilepsy (continued). "Taken together, our report suggests that significant intrafamilial phenotypic variability can be observed in GABRA1‐related seizure disorders." (PMID 31568673, 2019). "Heterozygous Gabra1-KO mice displayed spontaneous ethosuximide-sensitive spike and waves discharges suggesting this is an absence epilepsy gene that evolved to JME." (PMID 31611775, 2019). "Missense or nonsense mutations of GABRA1, GABRB3 and GABRG2 epilepsy genes are linked with classical GEs with autosomal dominant inheritance including, GEFS+, childhood absence epilepsy, febrile seizures, and juvenile myoclonic epilepsy." (PMID 27622563, 2016). "Mutations in several GABAAR subunit‐encoding genes, including the synaptic subunits GABRA1, GABRB3, and GABRG2 that associate with gephyrin, have been identified in epilepsy syndromes of different degrees of severity." (PMID 26613940, 2015). "Incorporation of an expression dataset from Gene Expression Omnibus (GEO) further highlighted two genes, CHRNA7 and GABRA1, which are differently expressed between epilepsy patients and controls." (PMID 21390307, 2011). "The observation of GABRA1 and GABRG2 in our network provides strong evidence of the association between GABAA receptors and epilepsy." (PMID 21390307, 2011). "GABRA1 was also identified to be differently expressed between epilepsy patients and controls in our analysis of expression data." (PMID 21390307, 2011). "Five genes, ABCB1, ABCB4, CHRNA7, GABRA1, and GABRG2, are located within reported CNV regions and have been studied previously for their association with epilepsy as collected by HuGE." (PMID 21390307, 2011). "In humans, however, the GABRA1 mutation would only exist in the α1 subunit of the GABAA receptor, likely indicating that some residual channel activity may be retained in epilepsy patients with this mutation." (PMID 38813985, 2024). "In the present study, we performed GABRA1 trio-based whole exome sequencing (WES) in patients with epilepsy without acquired cause." (PMID 38269327, 2023). "As one of the first phenotypes to be associated with GABRA1, juvenile myoclonic epilepsy is the most common IGE syndrome in adolescents and adults, accounting for approximately 9.3% of all epilepsy types, characterized by myoclonic jerks, GTCA, and absence seizures." (PMID 40217359, 2023). "GABRA1 pathogenic variants may attenuate the inhibitory function of GABA via haploinsufficiency, causing a broad spectrum of epilepsy phenotypes." (PMID 35937053, 2022). "Meta-analysis of GABRA1 rs2279020 and GABRA6 rs3219151 polymorphisms with the risk of epilepsy." (PMID 36188399, 2022). "However, a cohort in the phenotypic spectrum of GABRA1 showed a wide range of epilepsy subtypes spanning from benign forms to moderately severe phenotypes and severe DEEs, with 6% of patients exhibiting a GEFS+ phenotype." (PMID 35937053, 2022). "After searching in DrugBank, we retrieved a total of 47 anti-epileptic drugs and 151 targets, of which identified 17 target genes (CACNA1A, CHRNA4,CHRNA7,GABRA1,GABRA2,GABRB2,GABRG2,GRIK1,GRIN1,GRIN2B,KCNQ2,KCNQ3,SCN1A,SCN2A, SCN3A,SCN8A and SCN9A) were overlapped with risk genes of epilepsy." (PMID 36006933, 2022). "In conclusion, the present accumulated evidence revealed that neither the GABRA1 rs2279020 nor the GABRA6 rs3219151 polymorphism was a risk factor for the etiology of epilepsy and antiepileptic drug responsiveness in the Asian and Arabic populations." (PMID 36188399, 2022). "We found that neither the GABRA1 rs2279020 nor the GABRA6 rs3219151 polymorphism was a risk factor for the etiology of epilepsy and antiepileptic drug responsiveness." (PMID 36188399, 2022).
epilepsy (continued). "Meanwhile, we investigated whether epilepsy can be suppressed by the inhibition of miR‐129–2‐3p together with the silencing of GABRA1." (PMID 34029007, 2021). "However, when GABRA1 interfered by siRNA in hippocampus, the protective function of Anta‐129 was eliminated, which further indicated the involvement of miR‐129–2‐3p in epilepsy was related to its regulation on GABRA1." (PMID 34029007, 2021). "We found that variants in the epilepsy-associated genes GABRA1, GABRB3 and GABRG2 were mainly present in the ESP variants, but the GEC cohort contained epilepsy-associated GABRA6, GABRB1, and GABRB2 and non-epilepsy- associated GABRA4, GABRA5, and GABRG3 genes." (PMID 27622563, 2016). "Interestingly, two of the overlap genes, CHRNA7 and GABRA1, were also shown to be significantly differentially expressed between epilepsy patients and normal controls." (PMID 21390307, 2011). "One gene, GABRA1, which is an inherited human epilepsy gene, initially resulted in marginally significant p-values for two different microsatellites: 0.074 (first set) and 0.033 (second set), however, a third microsatellite's alleles resulted in an insignificant p-value of 0.890." (PMID 21518446, 2011). "Four de novo mutations in the GABRA1 variants were identified in six unrelated cases, including two with epilepsy with febrile seizures plus (EFS +), three with developmental and epileptic encephalopathy (DEE), and one with epilepsy with generalized tonic-clonic seizures alone (GTCA)." (PMID 38269327, 2023). "Whether and how GABRA1 mutations affect dendritic spines and GABAergic bouton formation, thus contributing to the epilepsy phenotype has not been so far examined." (PMID 25352779, 2014). "Therefore, we may conclude that the GABRA1 rs2279020 was not a risk factor for the occurrence of epilepsy." (PMID 36188399, 2022). "The two modules had the proteins, such as KCNA2, GABRA1, and GRIN2A, which had been recently be discovered as novel epilepsy genes." (PMID 28388656, 2017). "This meta-analysis suggests that GABRA1 rs2279020 and GABRA6 rs3219151 are not risk factors for the etiology of epilepsy and antiepileptic drug responsiveness in the Asian and Arabic populations." (PMID 36188399, 2022). "Meta-analysis of GABRA1 rs2279020 and GABRA6 rs3219151polymorphisms with drug-resistance epilepsy." (PMID 36188399, 2022). "GABRA1, along with GABRB3, is vital for the formation of GABAA receptors and plays a pivotal role in GABAergic signaling that protects neurons in the brain from over-signaling, which can often lead to diseases such as epilepsy." (PMID 33816350, 2021). "In these studies, Gabra1 regulation via ICER is independent of STAT3 phosphorylation, suggesting that neuronal signaling through both the canonical and non-canonical pathways may be relevant to epilepsy, and potentially to learning and memory." (PMID 39643584, 2025).
juvenile myoclonic epilepsy (20 papers, 2011 to 2026). "In a study including fifteen children with a variant of the GABRA1 gene, seven were treated with ASMs and remained seizure free, including two patients with juvenile myoclonic epilepsy and one patient with GEFS+ treated with VAP monotherapy." (PMID 35937053, 2022). "Mutation in GABRA1 has also been found in affected individuals of a large French Canadian family with juvenile myoclonic epilepsy." (PMID 34029007, 2021). "Particularly, mutations in the gene GABRA1 which encodes GABAA receptor subunit α1 have been identified as a causative factor for juvenile myoclonic epilepsies and idiopathic generalized epilepsies." (PMID 34029007, 2021). "GABRA1 variants were first identified in patients with idiopathic generalized epilepsy, specifically juvenile myoclonic epilepsy, childhood absence epilepsy, and generalized epilepsy with febrile seizures plus." (PMID 31707987, 2019). "Non-synonymous heterozygous variants in GABRA1 have been associated with juvenile myoclonic epilepsy." (PMID 25093588, 2014). "For example, increased expression of GABAA receptors was observed in the hippocampus of patients with temporal lobe epilepsy, and an Ala322Asp mutation in GABRA1 was found in juvenile myoclonic epilepsy patients." (PMID 21390307, 2011). "In patients with juvenile myoclonic epilepsy, several individual loci are involved, of which GABRA1, GABRD, EFHC1, BRD2, CASR, and ICK with complex inheritance are considered to be the most pathogenic." (PMID 39513854, 2024). "Missense or nonsense mutations of GABRA1, GABRB3, and GABRG2 are linked with GEFS+, childhood absence epilepsy, febrile seizures, and juvenile myoclonic epilepsy." (PMID 38003469, 2023). "Previously, the GABRA1 gene has been identified to be associated with developmental and epileptic encephalopathy (DEE) and idiopathic generalized epilepsy (IGE)." (PMID 38269327, 2023). "Previous studies have shown that mutations of the GABA receptors, such as, GABRA1, GABRA5, GABRA6, GABRB3, GABRD, GABRG2, were associated with idiopathic generalized epilepsy." (PMID 35663265, 2022). "In humans, the GABRA1 gene has been identified as the causative gene of developmental and epileptic encephalopathy-19 (DEE-19, OMIM* 615744) and the susceptibility genes of childhood absence epilepsy-4 (ECA-4, OMIM* 611136) and juvenile myoclonic epilepsy-5 (JME-5, OMIM* 611136)." (PMID 38269327, 2023). "On the other hand, mutations in the same gene could be found in different epilepsy phenotypes; for example, mutations in the GABRA1 gene are associated with EIEE, childhood absence epilepsy (CAE) and juvenile myoclonic epilepsy (JME)." (PMID 36428502, 2022). "The second candidate gene, GABRA1 has been associated with early infantile epileptic encephalopathy (EIEE19; MIM: 615744) and juvenile myoclonic epilepsy (EJM4, EJM5; MIM: 611136) and, therefore, became the primary putative candidate gene based on clinical phenotype." (PMID 32205311, 2020).
Epileptic encephalopathy (13 papers, 2018 to 2024). A condition in which epileptiform abnormalities are believed to contribute to the progressive disturbance in cerebral function. "Encephalopathy is characteristic of 112 IMDs (19%) that are often classified as developmental and epileptic encephalopathies (DEE) (e.g., early infantile epileptic encephalopathies due to GABRA1, GABRB1, GABRB2 or GABRB3 pathogenic variants)." (PMID 35328062, 2022). "We report the identification of a de novo GABRA1 (R214C) variant in a child with epileptic encephalopathy (EE), describe its functional characterization and pathophysiology, and evaluate its potential therapeutic options." (PMID 31707987, 2019). "A mutation in GABRA1 has been reported in epileptic encephalopathy in children." (PMID 36389068, 2022). "While conventional DNA sequencing confirmed the presence of the variant in the affected individual, it was shown to be absent in DNA isolated from both parents, leading to a genetic diagnosis compatible with early infantile epileptic encephalopathy, caused by a de novo missense variant in GABRA1." (PMID 32047208, 2020). "Finally, mutations in both Gabra1 and Gabra5 genes, which are dysregulated in our mice, leading to functional hypoactivity of the GABAergic system, are associated with the genetic etiology of both benign and severe epilepsy syndrome and early-onset epileptic encephalopathies." (PMID 39583831, 2024). "The phenotypic spectrum observed for GABRG2 variants, ranging from febrile seizures to epileptic encephalopathy, is similar to those of the other GABAA receptor genes GABRA1, GABRB2, and GABRB3." (PMID 35359574, 2022). "Currently, patients with the GABAA receptor-related GABRA1 and GABRG2 genes, ranging from genetic generalized epilepsy to epileptic encephalopathy, have been found to be photosensitive." (PMID 36034301, 2022).
generalized epilepsy (13 papers, 2014 to 2026). Epilepsy that is characterized by generalized seizure types and may have typical interictal and/or ictal EEG findings that accompany generalized seizure types (for example generalized spike-wave). "Epileptic disorders caused by pathogenic variants in GABRA1 cause a wide range of clinical symptoms, including mild generalized epilepsies and severe infantile DEEs." (PMID 35937053, 2022). "In particular, we examined the effects of three mutations of the GABRA1 gene (D219N, A322D and K353delins18X) that were found in a cohort of French Canadian families with genetic generalized epilepsy." (PMID 25352779, 2014). "Mutations in genes encoding GABAA receptor subunits, such as GABRA1, GABRB3, GABRG2, and GABRD, have been identified in patients with idiopathic generalized epilepsies, Dravet syndrome, childhood absence epilepsy, and febrile seizures." (PMID 41614796, 2025). "There are also variants in GABRA1, GABRB3 or GABRG2 that are all associated with GGEs ranging from CAE, generalized epilepsy with febrile seizures plus (GEFS+), myoclonic atonic epilepsy (MAE) to other developmental EEs." (PMID 34095830, 2021).
Anxiety (11 papers, 2018 to 2026). Intense feelings of nervousness, tension, or panic often arise in response to interpersonal stresses. "This reduction in Gabra1 expression could be associated with altered GABAergic signaling, which could contribute to observed behavioural changes, such as increased marble burial and anxiety." (PMID 38566972, 2024). "There is evidence showing that GABRA1 can improve anxiety behavior in rats." (PMID 36386232, 2022). "Currently, though the alteration of GABAA and 5-HT receptors under strong oxidative stimulation is unclear, our result in some extent suggested that overexpression of GABRA1, GABRA2, HTR1A, HTR1B, and HTR2A may be involved in oxidative stress-induced anxiety." (PMID 33178009, 2020).
Dravet syndrome (11 papers, 2012 to 2024). "Next-generation sequencing on 870 patients with Dravet syndrome identified nine variants in GABRA1, GABRB2 and GABRG2 genes, which encode the most common α1β2γ2 GABAA receptor in the CNS." (PMID 34095830, 2021). "In this study, we identified nine patients with Dravet syndrome caused by variants in three relevant, but different, genes, GABRA1, GABRB2 or GABRG2." (PMID 34095830, 2021). "Therefore, pathogenic variants in the GABRA1 gene may present with both typical and atypical Dravet syndrome phenotypes." (PMID 35937053, 2022). "Mutations in GABRs, especially in GABRA1, GABRB2, GABRB3, and GABRG2, impair GABAergic signaling and are frequently associated with DEEs such as Dravet syndrome and Lennox–Gastaut syndrome, as GABAergic signaling is critical for early brain development." (PMID 36077081, 2022). "There are variants in GABRA1, GABRB2 or GABRG2 that are all associated with Dravet syndrome." (PMID 34095830, 2021). "Using the advantage of next-generation sequencing (NGS) technologies, we discovered nine novel de novo variants in GABRA1, GABRB2 and GABRG2 that were associated with Dravet syndrome and code for subunits that form the most common GABAA receptor (the α1β2γ2 receptor)." (PMID 34095830, 2021). "Recently, GABAA receptor subunit genes (GABRs) encoding α1 (GABRA1), β3 (GABRB3) and γ2 (GABRG2), but not β2 (GABRB2) or β1 (GABRB1), subunits are frequently associated with Dravet syndrome or Dravet syndrome-like phenotype." (PMID 34095830, 2021).
glioma (6 papers, 2009 to 2022). A benign or malignant brain and spinal cord tumor that arises from glial cells (astrocytes, oligodendrocytes, ependymal cells). "Furthermore, we explore the possible role of miR-139-5p and GABRA1 in the development of glioma and the underlying molecular regulation mechanism." (PMID 34001135, 2021). "It has been shown that overexpression of miR-139-5p in vitro leads to the inhibition of cell proliferation, migration and invasion of glioma by targeting gamma-aminobutyric acid A receptor alpha 1 (GABRA1)." (PMID 36354672, 2022). "We identified six hub genes (RAB3A, TYROBP, SYP, CAMK2A, VSIG4, and GABRA1) that predicted the prognosis of glioma." (PMID 36072978, 2022). "Higher expression levels of RAB3A, SYP, CAMK2A, and GABRA1, as well as lower expression levels of TYROBP and VSIG4, in glioma patients were associated with improved OS and DFS." (PMID 36072978, 2022). "Taken together, our data indicated that miR-139-5p modulates glioma cell migration and invasion by targeting GABRA1." (PMID 34001135, 2021). "The results revealed that the restoration of GABRA1 markedly reversed miR-139-5p-mediated glioma inhibitory effects." (PMID 34001135, 2021). "Another study showed that GABRA1 was expressed in gliomas, and that the expression level was highest in WHO grade II gliomas." (PMID 34001135, 2021). "There are few studies on the relationship between GABRA1 expression and gliomas, and any that do exist have been controversial in regard to the expression level of GABRA1 in gliomas." (PMID 34001135, 2021). "MiR-139-5p regulates glioma cell migration and invasion through targeting of GABRA1." (PMID 34001135, 2021). "Finally, we validated that miR-139-5p affected glioma malignant biological behavior via targeting gamma-aminobutyric acid A receptor alpha 1(GABRA1) through rescue experiments." (PMID 34001135, 2021). "Our experimental results in vitro suggest that GABRA1 is expressed in the glioma cell lines U251 and U87, and through overexpression and silencing experiments, we found that GABRA1 plays a role in promoting the growth of gliomas, which is directly regulated by miR-139-5p." (PMID 34001135, 2021). "Moreover, we found that miR-139-5p exerted tumor anti-tumor functions in glioma by directly targeting GABRA1." (PMID 34001135, 2021). "Therefore, it could be concluded that RAB3A, TYROBP, SYP, CAMK2A, VSIG4, and GABRA1 may play a critical role in glioma by regulating immune cells." (PMID 36072978, 2022). "Specifically, we identified that miR-139-5p and GABRA1 served as inverse agents in the regulation of malignant phenotypes of glioma cells, we doubted whether the function of miR-139-5p on glioma cells was mediated through its inhibitory impression on GABRA1 expression." (PMID 34001135, 2021). "After a series of database screening tests, we identified 11 modules during glioma progression, followed by six hub genes (RAB3A, TYROBP, SYP, CAMK2A, VSIG4, and GABRA1) that can predict the prognosis of glioma and were validated in glioma tissues by qRT-PCR." (PMID 36072978, 2022). "Six hub genes related to glioma diagnosis and prognosis were identified, including RAB3A, TYROBP, SYP, CAMK2A, VSIG4, and GABRA1." (PMID 36072978, 2022). "The effect of GABRA1 expression on the malignant biological behavior of glioma has not been reported." (PMID 34001135, 2021).
autism (5 papers, 2018 to 2023). Persistent deficits in social interaction and communication and interaction as well as a markedly restricted repertoire of activity and interest as well as repetitive patterns of behavior. "As the child nodes of hub genes, these genes are directly regulated, including known AD-related genes (GABRA1, SYN1, SORSC3, STXBP) and autism risk gene (CHD8)." (PMID 33298176, 2020). "A recent study reported widely decreased expression of genes encoding different subunits of GABA-AR, including GABRA1, GABRA2, GABRA3, GABRB3, GABBR1, and GABBR2, which is consistent with an earlier study reporting reduced GABRA1, GABRA5, and GABRB2 levels in the cortex of VPA-induced autism models." (PMID 35198562, 2021).